LMNA (lamin A/C)
Diseases named in the same sentence as LMNA in open-access papers (continued):
Sharing a sentence is not in itself a finding about the gene and the disease.
lung adenocarcinoma (2 papers, 2017 to 2018). A carcinoma that arises from the lung and is characterized by the presence of malignant glandular epithelial cells. "A strong reduction in lamin A but not in lamin C expression was specifically observed in 12 (37.5%) patients with lung adenocarcinoma pleural metastasis using a mouse anti-lamin A/C antibody (Jol2)." (PMID 28806747, 2017).
mesenchymal neoplasms (2 papers, 2013 to 2021). "To date, most of the fusions described in mesenchymal neoplasms involve NTRK1 and NTRK3 genes and include different fusion partner genes, most common being ETV6, LMNA, and TPM3." (PMID 32860002, 2021).
motor neuron diseases (2 papers, 2021 to 2022). "However, following the terminology used for diseases caused by lamin A/C (LMNA) gene mutations, all diseases caused by BSCL2 mutations (CGL2, PELD, and BSCL2-associated motor neuron diseases) should be called “seipinopathies”." (PMID 35740965, 2022).
myocardial disease (2 papers, 2017 to 2023). "Lastly the nature of the change to the LMNA isoforms is very similar but more severe than one seen in humans which can cause myocardial disease." (PMID 37925523, 2023). "The rapid development of myocardial disease could be due to unidentified modifier genes in each case, yet the veracity of this genotype-phenotype association is compelling insofar as both children had the same LMNA mutation and nearly identical clinical courses." (PMID 29367541, 2017).
myocardial inflammation (2 papers, 2024 to 2025). "We present two cases of young male patients, both with mutations in the DSP and LMNA genes, who initially presented with symptoms of myocardial inflammation." (PMID 41040932, 2025). "Studies have reported that up to 22% of patients initially diagnosed with myocarditis carry such mutations, with DSP, LMNA, and TTN being the most frequently implicated genes." (PMID 41040932, 2025). "Although these studies used DSP disruption as its genetic model of myocarditis, many other genes have been implicated in this process, including TTN, LMNA, FLNC, PKP2, and others." (PMID 38768074, 2024).
peripartum cardiomyopathy (2 papers, 2020 to 2025). Peripartum cardiomyopathy (PPCM) is an idiopathic, potentially fatal form of dilated cardiomyopathy that develops during the final month of pregnancy or within five months after delivery. "AF families have been identified carrying mutations in cytoskeletal proteins, including lamin A/C (LMNA) and desmin, which have been associated with dilated (DCM) and peripartum cardiomyopathy (PPCM) onset." (PMID 32411727, 2020).
sarcopenia (2 papers, 2014 to 2023). Progressive decline in muscle mass due to aging which results in decreased functional capacity of muscles. "Its reduced association with lamin A/C in IL10-KO muscle suggests Lmcd1 is also relevant to sarcopenia and fatigue in frailty and warrants further testing." (PMID 37936983, 2023). "Decline in human muscle mass and strength (sarcopenia) is a hallmark of the aging process; whether methylation changes in genes such as LMNA, TNNT3, ELN and HDAC4 are a cause or consequence of this process merits investigation." (PMID 24112369, 2014).
scoliosis (2 papers, 2023 to 2025). A congenital or acquired spinal deformity characterized by lateral curvature of the spine. "Among the identified variants, FLNB and LMNA, both associated with autosomal dominant disorders that include scoliosis in their phenotypic spectrum, emerge as particularly significant contributors to severe IS, with FLNB showing statistical enrichment compared to controls (p < 0.05)." (PMID 41210864, 2025).
spinal muscular atrophy (2 papers, 2015 to 2021). A motor neuron disease that affect the muscles, and characterized by muscle weakness and atrophy resulting from progressive degeneration and irreversible loss of the anterior horn cells in the spinal cord (i.e., lower motor neurons) and the brain stem nuclei. "The concept that lamin A/C gene mutations cause spinal muscular atrophy has not been established." (PMID 25886484, 2015).
thromboembolic disease (2 papers, 2022 to 2025). "More interestingly, based on the cosegregation of clinical phenotypes and genotypes, our important finding first demonstrated that LMNA p.A242V might be associated with aberrant ARVC/D, severe low-limb edema induced by RVHF and thromboembolism, especially cerebral thromboembolism." (PMID 35526016, 2022).
-dependent (1 paper, 2018). "Loss of adipose tissue is another typical feature of HGPS, as well as of the other LMNA-dependent lipodystrophic syndromes; affected patients present complete or partial fat atrophy (lipoatrophy) and metabolic defects (such as insulin resistance)." (PMID 30619852, 2018).
autosomal recessive Emery-Dreifuss muscular dystrophy (1 paper, 2024). Autosomal recessive form of Emery-Dreifuss muscular dystrophy. "Pathogenic variants in the LMNA gene cause, among other conditions, autosomal dominant Emery-Dreifuss muscular dystrophy type 2 (EDMD2; MIM 181350), and the Slovenian type hand-heart syndrome (MIM 610140), as well as autosomal recessive Emery-Dreifuss muscular dystrophy type 3 (EDMD3; MIM 616516)." (PMID 39687831, 2024).
breast tumor (1 paper, 2023). "There was a slight downregulation of LMNA in breast tumor tissues while LMNB1 and LMNB2 were significantly upregulated." (PMID 37218524, 2023).
calcification (1 paper, 2025). Process by which organic tissue becomes hardened by the physiologic deposit of calcium salts. "In conclusion, this report describes the first association, to our knowledge, between the homozygous LMNA c.785A > G (p.Glu262Gly) mutation and severe, early-onset cardiac valvular calcification manifesting as a prominent feature within the MADA phenotype." (PMID 41357091, 2025).
cervical cancer (1 paper, 2017). A primary or metastatic malignant neoplasm involving the cervix. "Indeed, besides studies linking lamin A/C downregulation to HPV infection, more recently, Capo-chichi and colleagues suggested that lamin A/C deficiency may serve as an independent risk factor for CIN development and as an indicator for preventive therapy in cervical cancer." (PMID 29212225, 2017).
Charcot-Marie-Tooth disease type 2 (1 paper, 2008). A Charcot-Marie-Tooth disease characterized by abnormalities in the axon of the peripheral nerve cell. "For example, a form of the hereditary motor and sensory neuropathy, Charcot-Marie-Tooth disease, type 2 (CMT2), is caused by mutations in the LMNA gene, encoding lamin A." (PMID 18840504, 2008).
Cognitive impairment (1 paper, 2023). Abnormal cognition is characterized by deficits in thinking, reasoning, or remembering. "Seven differentially expressed autoantibodies were recognised as cognitive impairment-related, including HSPD1, CDK19, TKT, BRSK2, NRAS, LMNA, and CAMK2A." (PMID 38107644, 2023).
craniosynostosis (1 paper, 2018). Craniosynostosis is defined as the premature fusion of one or more cranial sutures leading to secondary distortion of skull shape resulting in skull deformities with a variable presentation. "This slight overexpression may contribute to craniosynostosis but is rather inconsistent with muscular hypotonia, as this feature is related to decreased level of LMNA." (PMID 29845577, 2018).
dilatation (1 paper, 2025). "Desmosomal (PKP2, DSG2), lamin (LMNA) and truncating FLNC variants destabilize the cytoskeleton, activate inflammatory and adipogenic programmes and shorten action-potential duration, changes that favor ventricular arrhythmias long before global LV dilatation." (PMID 40742635, 2025).
endothelial dysfunction (1 paper, 2023). In vascular diseases, endothelial dysfunction is a systemic pathological state of the endothelium (the inner lining of blood vessels) and can be broadly defined as an imbalance between vasodilating and vasoconstricting substances produced by (or acting on) the endothelium. "VSMC injury might also contribute to the endothelial dysfunction reported in LMNA-DCM patients since aortic rings lacking lamin A/C specifically in VSMCs had depressed endothelium-dependent acetylcholine-induced relaxation despite normal lamin A/C expression in ECs." (PMID 37446344, 2023).
fibromatosis (1 paper, 2017). A poorly circumscribed neoplasm arising from the soft tissues. "Since all four family members affected with fibromatosis were double heterozygotes for the LMNA mutation c.736C>T (p.Gln246Stop) and ASTE1 c.230T>C (p.Val77Ala), it is possible that both Lamin A/C haploinsufficiency and an ASTE1 defect are required for disease." (PMID 29104234, 2017).
fibrosis (1 paper, 2023). the formation of excess fibrous connective tissue in an organ or tissue in a reparative or reactive process. "Like mice with whole body or cardiomyocyte-specific lamin A/C ablation, Lmnaflox/floxSM22αCre mice recapitulated the main hallmarks of human LMNA-DCM, including ventricular systolic dysfunction, cardiac conduction defects, cardiac fibrosis, and premature death." (PMID 37446344, 2023).
head and neck cancer (1 paper, 2023). A primary or metastatic malignant neoplasm affecting the head and neck. "However, the development of hypopharyngeal squamous cell carcinoma in the absence of any other risk factors for head and neck cancer has been reported in two biological sisters with the R349W variant in the LMNA gene." (PMID 36899861, 2023).
idiopathic scoliosis (1 paper, 2018). A scoliosis with no known cause. "In a pilot study, we tested the hypothesis that LMNA mutations could also occur in early onset idiopathic scoliosis." (PMID 29854317, 2018).
ischemic cardiomyopathy (1 paper, 2025). Ischemic cardiomyopathy is a cardiomyopathy in which a weakness in the muscle of the heart due to inadequate oxygen delivery to the myocardium with coronary artery disease being the most common cause. "Regarding genetic testing, in a study of 487 individuals with non‐ischemic cardiomyopathy, pathogenic gene variants were identified in 37% of patients, and the patients with LMNA, a nuclear membrane lining protein, had a significantly higher risk of SCD and fatal arrhythmias." (PMID 40524851, 2025).
male infertility (1 paper, 2021). The inability of the male to effect fertilization of an ovum after a specified period of unprotected intercourse. "Interestingly, H1T2-bound chromatin also interacts with lamin A/C protein encoded by LMNA gene, whose function is essential for cytoskeletal dynamics associated with spermatogenesis and its disruption leads to male infertility." (PMID 33407810, 2021).
mitral valve stenosis (1 paper, 2024). Narrowing of the left atrioventricular mitral orifice. "This case series describes two families in which two novel LMNA-gene variants were identified, and who presented with an atypical progeroid phenotype with primarily premature aortic and mitral valve stenosis." (PMID 38535109, 2024).
motor neuron degeneration (1 paper, 2026). "Analysis of bulk RNA-sequencing data from an additional cohort identified deleterious somatic variants in DYNC1H1 and LMNA, genes associated with pediatric motor neuron degeneration." (PMID 41986690, 2026).
myofibrillar myopathy (1 paper, 2025). "Truncating variants in TTN are strongly associated with DCM, while mutations in DSP, LMNA, MYH7, RBM20, TNNT2, BAG3, and FLNC (the latter being linked to myofibrillar myopathy) are also commonly implicated." (PMID 39857686, 2025).
myositis (1 paper, 2018). "More careful analysis of potential causes of the muscle pathology may reveal greater overlap between the lipodystrophy syndromes, myositis, and muscle diseases associated with lamin A/C mutations than previously suggested." (PMID 29610677, 2018).
neurodevelopmental disabilities (1 paper, 2019). "The ZMPSTE24 gene mutated in MADB patients encodes the zinc metalloprotease enzyme involved in production of mature lamin A. We therefore hypothesize that downregulation of LMNA transcripts in the brain might also explain the lack of neurodevelopmental disabilities in MADB patients." (PMID 31856865, 2019).
neutropenia (1 paper, 2021). A decrease in the number of neutrophils found in the blood. "In the present study, we observed that a variant located in the LMNA gene locus was associated with neutropenia in AFR ancestry but not in other ancestry groups, including EUR which would have been well powered to detect an association." (PMID 34642702, 2021).
osteoarthritis (1 paper, 2023). A noninflammatory degenerative joint disease occurring chiefly in older persons, characterized by degeneration of the articular cartilage, hypertrophy of bone at the margins and changes in the synovial membrane. "Four target genes (LMNA, MSN, PDCD6IP, and GAPDH) with five miRNAs (hsa-let-7a-5p, hsa-let-7b-5p, hsa-mir-15a-5p, hsa-mir-26a-5p, and hsa-mir-23b-3p) were associated with the pathway in osteoarthritis according to the results of the miRNet network analysis." (PMID 38132172, 2023).
ovary (1 paper, 2018). "In breast, liver, and ovary cancers, the ratio of lamin C-derived mRNA splice variant to that of lamin A-derived mRNA splice variant is greater in metastatic cells than their healthy counterparts as LMNA mRNA splice variants coding for lamin C isoforms increase while lamin A isoforms decrease." (PMID 30450357, 2018).
pancreatic disease (1 paper, 2023). "Among these proteins, six (AAT, IGFBP2, RAB2B, PRDX2, RHOC, and LMNA) with functions closely related to pancreatic disease were selected for further validation." (PMID 36712921, 2023).
plantar fibromatosis (1 paper, 2017). A superficial fibromatosis arising from soft tissue of the plantar regions. "We report a family with cardiac disease due to a heterozygous LMNA mutation (c.736C>T, p.Gln246Stop) with palmar/plantar fibromatosis and investigate the hypothesis that a second rare DNA variant increases the risk for fibrotic disease in LMNA mutation carriers." (PMID 29104234, 2017).
progeria-like syndrome (1 paper, 2022). "Here, using reprogrammed cells from patients affected with HGPS, progeria-like syndrome (HGPS-L) or APS, we have broadened the description of the phenotypic cellular alterations linked to causative LMNA mutations." (PMID 36104080, 2022).
protein deficiency (1 paper, 2013). "In fact, a synergistic effect derived from the LMNA mutation combined with protein deficiency appears likely in vivo." (PMID 23804595, 2013).
schizophrenia (1 paper, 2018). A major psychotic disorder characterized by abnormalities in the perception or expression of reality. "The SLC25A5, NONO, LMNA and RPS3A proteins were not chosen for validation because little information about the relation between schizophrenia and these proteins is available." (PMID 29514709, 2018).
scleroderma (1 paper, 2022). Scleroderma is a rare autoimmune connective tissue disorder characterized by abnormal hardening of the skin and, sometimes, other organs. "ES revealed the rare diagnosis of heterozygous LMNA mutation causing Familial Lipodystrophy type 2 (Dunnigan type), a previously reported cause for scleroderma-like presentation." (PMID 36699461, 2022).
cancer (58 papers, 2009 to 2025). A tumor composed of atypical neoplastic, often pleomorphic cells that invade other tissues. "Reduced LMNB1 gene expression was connected to a worse outcome, while greater LMNA gene expression has been associated with initial cancer stages." (PMID 38202898, 2023). "On the other end, overexpression of lamin A/C has been observed in prostate and colorectal cancers where the alteration of lamins has been associated with an increased capability of cancer cells to invade surrounding tissues." (PMID 36096808, 2022). "In our study, we demonstrated that lamin A/C deficiency in different types of cancer cells slows down cell growth both in vitro and in vivo and restricts lung metastasis." (PMID 34069191, 2021). "Mutations of the lamin A/C gene, incorrect processing of the protein, and lamin A/C deregulation can lead to various diseases and cancer." (PMID 33316938, 2020). "Because of the high prevalence of aneuploidy after Lamin A/C-suppression, it has been suggested that a nuclear envelope defect, resulting from loss or severe reduction of Lamin/C proteins, underlies the main cause of aneuploidy in cancer." (PMID 30524960, 2018). "The question of whether mutations in other CMY associated genes, apart from RAS/MAPK and LMNA, can impact on vulnerability of cancer remains unanswered." (PMID 32498335, 2020). "However, we suggest that a nuclear defect (loss of Lamin A/C proteins) is the common (more than 80% of cancers show nuclear deformation) cause of chromosomal instability and aneuploidy." (PMID 30524960, 2018). "While LMNB1 protein levels were reduced, both senescent MCF7 and A549 cancer cells displayed increased nuclear staining for both LMNA and LMNB1." (PMID 41159617, 2025). "Primary breast epithelial cells with lamin A/C expression knocked down by shRNA exhibit cancer-like shape and aneuploidy." (PMID 38202898, 2023). "Knockdown of lamin-A/C using shRNA reveals nuclear morphological deformation of primary breast epithelial cells, be similar to phenotype of cancer cells." (PMID 37250905, 2023). "In contrast, other studies have indicated that LMNA expression decreases in endometrial, colon, and breast cancers." (PMID 35805203, 2022). "On one hand, lamin A/C expression is reduced in several solid cancers, and cancer progression was suggested to correlate with lower lamin A/C expression." (PMID 34069191, 2021). "In contrast, increased YAP nuclear localization and activity in combination with reduced lamin levels is observed in cancers of many organ types, as well as in LMNA mutant MuSCs cultured on soft matrices." (PMID 32231000, 2020). "TGFB3 and LMNA were both more frequently repositioned in low T stage cancers to that of high T stage cancers, but with high false positive rates." (PMID 31681438, 2019). "However, the molecular mechanism underlying the loss of lamin A/C in human cancer remains unknown." (PMID 19144202, 2009). "We identified a previously unrecognized feature of senescent cancer cells: an increase in LMNA and LMNB1 nuclear staining intensities despite reduced LMNB1 protein levels by immunoblot, which is in contrast to the typical reduction seen in primary senescent fibroblasts." (PMID 41159617, 2025). "Notably, these recurrent SLRs were associated with genes known to be implicated in cancer, as evidenced by the Catalogue of Somatic Mutations in Cancer (COSMIC), including RALGDS, BCR, SH2B3, LMNA, and GATA2." (PMID 40193528, 2025). "Among the 24 cancer types investigated, we found both B‐type lamins: lamin B1 and lamin B2 showed significant enrichment in tumor tissues (22/24 and 23/24 tumor types investigated, respectively), but LMNA was only enriched in 9/24 cancer types." (PMID 37218524, 2023). "Despite the fact that somatic mutations in the LMNA gene can occur in a variety of tumor types, these mutations are rare, and the mutation frequency does not exceed 3% in all cancer types analyzed by TCGA projects." (PMID 38067205, 2023).